STX4 (syntaxin 4)
Description:
Plasma membrane t-SNARE that mediates docking of transport vesicles (By similarity). Necessary for the translocation of SLC2A4 from intracellular vesicles to the plasma membrane (By similarity). In neurons, recruited at neurite tips to membrane domains rich in the phospholipid 1-oleoyl-2-palmitoyl-PC (OPPC) which promotes neurite tip surface expression of the dopamine transporter SLC6A3/DAT by facilitating fusion of SLC6A3-containing transport vesicles with the plasma membrane (By similarity). Together with STXB3 and VAMP2, may also play a role in docking/fusion of intracellular GLUT4-containing vesicles with the cell surface in adipocytes and in docking of synaptic vesicles at presynaptic active zones (By similarity). Required for normal hearing.
Synonyms: STX4A; p35-2; DFNB123
Tractability: Antibody: its Gene Ontology location is reachable by antibodies, with high confidence; UniProt places it where antibodies can reach, with medium confidence; UniProt predicts a signal peptide or a membrane-spanning region; the Human Protein Atlas places it where antibodies can reach. PROTAC: ubiquitination databases record sites on it; its protein half-life has been measured.
Gene: Protein-coding gene on chromosome 16 (31,032,889 to 31,042,975, forward strand). Ensembl gene ENSG00000103496.
Subcellular location: Cell membrane; Cell projection, neuron projection; Cell projection, stereocilium; Cytoplasm, perinuclear region
Subcellular location (Human Protein Atlas): Plasma membrane
Pathways (Reactome):
Immune System: ER-Phagosome pathway; Other interleukin signaling
Vesicle-mediated transport: Translocation of SLC2A4 (GLUT4) to the plasma membrane; trans-Golgi Network Vesicle Budding
Hemostasis: Disinhibition of SNARE formation
Gene Ontology:
Molecular function: protein binding; sphingomyelin phosphodiesterase activator activity; SNARE binding; SNAP receptor activity
Biological process: cellular response to oxidative stress; cornified envelope assembly; long-term synaptic potentiation; organelle fusion; positive regulation of catalytic activity; positive regulation of cell adhesion; positive regulation of cell migration; positive regulation of cell population proliferation; positive regulation of chemotaxis; positive regulation of eosinophil degranulation; positive regulation of immunoglobulin production; positive regulation of insulin secretion involved in cellular response to glucose stimulus; positive regulation of protein localization to cell surface; positive regulation of protein localization to plasma membrane; regulation of exocytosis; regulation of extrinsic apoptotic signaling pathway via death domain receptors; sensory perception of sound; cellular response to starvation; exocytosis; macroautophagy; protein localization to cell surface; vesicle fusion; intracellular protein transport; regulation of postsynaptic membrane neurotransmitter receptor levels; SNARE complex assembly; and 1 more
Cellular component: basolateral plasma membrane; cell surface; dendritic spine; endosome; extracellular exosome; extracellular region; glutamatergic synapse; lamellipodium; membrane; plasma membrane; postsynapse; SNARE complex; somatodendritic compartment; specific granule; synapse; autophagosome membrane; cytosol; lysosomal membrane; neuron projection membrane; perinuclear region of cytoplasm; phagocytic vesicle membrane; stereocilium; vacuole; cytoplasm; lateral loop; and 6 more
Genetic constraint (gnomAD): Loss-of-function variants: 24 observed, 40.43 expected, observed/expected ratio (o/e) 0.59, 90% interval 0.43 to 0.83. The upper end of that interval is the gene's LOEUF score, 0.83, which puts it in group 3 of 6, group 1 being the genes least tolerant of losing a copy. Missense variants: 316 observed, 394.62 expected, observed/expected ratio (o/e) 0.8, 90% interval 0.73 to 0.88. Synonymous variants: 158 observed, 155.69 expected, observed/expected ratio (o/e) 1.01, 90% interval 0.89 to 1.16.
Homologues: Orthologues: chimpanzee STX4 (100% identical), rabbit STX4 (96% identical), dog STX4 (95% identical), pig STX4 (93% identical), mouse Stx4a (90% identical), guinea pig STX4 (87% identical), rat Stx4 (86% identical), macaque STX4 (65% identical), zebrafish stx4 (53% identical), tropical clawed frog stx4 (51% identical), Drosophila melanogaster Syx1A (40% identical), Caenorhabditis elegans unc-64 (36% identical). Paralogues in human: STX1B (46% identical), STX1A (44% identical), STX2 (43% identical), STX3 (39% identical), STX11 (26% identical), STX19 (25% identical), STX5 (25% identical), STX16 (24% identical), STX12 (21% identical), STX7 (19% identical), STX17 (16% identical), TSNARE1 (14% identical).
Diseases named in the same sentence as STX4 in open-access papers:
STX4 is named in the same sentence as 49 diseases in open-access papers, as found by Europe PMC text mining. Sharing a sentence is not in itself a finding about the gene and the disease. The quoted sentences say what the papers report.
diabetes (7 papers, 2008 to 2022). "In mice, decreased Syntaxin 4 content has been associated with insulin resistance during a clamp and following streptozotocin-induced diabetes." (PMID 18652694, 2008). "In the skeletal muscle of diabetic mice, STX4 mRNA levels are significantly reduced, suggesting that STX4 deficiency may be important for diabetes development, and that re-expression of STX4 may be a therapeutic strategy to restore insulin sensitivity and reverse T2D." (PMID 35774142, 2022). "This work supports further investigation of skeletal muscle STX4 enrichment as a therapy to prevent or reverse diabetes." (PMID 35058456, 2022). "Marked reduction in STX4 protein in the T2D donor islets (~70% reduction) and significant improvement of GSIS in otherwise secretion-deficient T2D islets following STX4 replenishment holds the key to the therapeutic potential of STX4 in diabetes treatment." (PMID 33673206, 2021). "In addition to the regulatory role for STX4 in β-cell inflammatory signaling, DOC2b ameliorates β-cell stress during diabetes." (PMID 33673206, 2021).
Insulin resistance (7 papers, 2008 to 2025). Increased resistance towards insulin, that is, diminished effectiveness of insulin in reducing blood glucose levels. "Here, the authors show that skeletal muscle-specific STX4 enrichment reverses established insulin resistance and improves mitochondrial function in the context of diabetogenic stress." (PMID 35058456, 2022). "Here, we show that transgenic skeletal muscle-specific STX4 enrichment (skmSTX4tg) in mice reverses established insulin resistance and improves mitochondrial function in the context of diabetogenic stress." (PMID 35058456, 2022). "In alignment with this point of view, a recent study showed that enrichment of STX4 (~2 fold) in skeletal muscle remediates peripheral insulin resistance in obese mice, even under conditions of persisting intake of high-fat diet." (PMID 35774142, 2022). "After 4 additional weeks (22 weeks old), the HFD and HFD + STX4 mice were re-assessed for insulin resistance." (PMID 35058456, 2022). "Collectively, these findings highlight the important role and therapeutic potential of STX4 in remediating insulin resistance in skeletal muscle." (PMID 35774142, 2022). "We tested if the amount of Munc18c and Syntaxin 4 in skeletal muscle differ in obese and lean humans, and if the relative expression changes in response to the acute induction of insulin resistance via fasting." (PMID 18652694, 2008). "Taken together, our results revealed SLN-RES could be a modern and interestingly therapeutic approach for the improvement of insulin resistance through targeting the expression of Snap23, Stx4, and Vamp2 in adipose and muscle tissues." (PMID 31290033, 2019). "Over expression of Munc18c relative to Syntaxin 4 in skeletal muscle leads to insulin resistance." (PMID 18652694, 2008). "Heterozygous knockout of Syntaxin 4 in mice also results in insulin resistance." (PMID 18652694, 2008). "Therefore, the defects in the insulin signaling pathway observed at the protein level, including Munc18c, PKCζ, phospho-PKCζ, and Syntaxin-4 in PCOS patients with insulin resistance, could lead to impaired glucose uptake." (PMID 22390153, 2012). "We have shown that STX4, a SNARE protein known for its regulation of GLUT4 translocation and glucose uptake in skeletal muscle, is capable, when enriched, of reversing established HFD-induced insulin resistance." (PMID 35058456, 2022). "Our data differ from animal studies and suggest Syntaxin 4 content may not be involved in short-term regulation of insulin action in humans, and may not be important to obesity-induced insulin resistance." (PMID 18652694, 2008).
Obesity (3 papers, 2008 to 2022). Accumulation of substantial excess body fat. "Syntaxin 4 content was not altered by obesity or fasting duration." (PMID 18652694, 2008).
Parkinson disease (3 papers, 2018 to 2021). A progressive degenerative disorder of the central nervous system characterized by loss of dopamine producing neurons in the substantia nigra and the presence of Lewy bodies in the substantia nigra and locus coeruleus. "The rs2303222 variant targets one more gene, STX4, and our results suggest that this candidate contributes exclusively to Parkinson’s disease." (PMID 29745862, 2018). "The corresponding protein, syntaxin 4, is involved in synaptic plasticity in hippocampal neurons but has not been previously documented to be associated with Parkinson’s disease, although the synaptic plasticity in the motor cortex was linked to skill learning in mice." (PMID 29745862, 2018).
adenoma (2 papers, 2014 to 2024). A neoplasm arising from the epithelium. "The anatomical data were confirmed by qPCR detection of the three transcripts in both INS-1E [rat insulinoma; (ΔCT values: 15.2 (Gapdh), 20.6 (Stx4), 20.2 (Snap25), and 17.1 (Scgn)) and αTC1-6 cell lines (mouse adenoma; ΔCT values: 14.3 (Gapdh), 31.1 (Stx4), 17.9 (Snap25), and 28.0 (Scgn)]." (PMID 38593081, 2024).
clear cell renal carcinoma (2 papers, 2023 to 2024). A malignant epithelial neoplasm of the kidney characterized by the presence of lipid-containing clear cells within a vascular network. "The elevated expression level of STX4 is also correlated with poor prognosis in the clear cell renal carcinoma." (PMID 37007952, 2023).
prediabetes (2 papers, 2022 to 2025). "This suggests that targeting STX4 might also reverse prediabetes in humans, even in the continued presence of diabetogenic stress." (PMID 35058456, 2022). "Thus, our work shows that STX4 is a critical component in skeletal muscle mitochondrial homeostasis, providing support for therapeutic targeting of STX4 to improve mitochondrial health in metabolic disorders such as prediabetes and T2D." (PMID 41214862, 2025).
Sjögren’s syndrome (2 papers, 2018). "In patients with primary Sjögren’s syndrome, STX4 gene and protein expression is decreased in labial salivary glands, while STX3 gene and protein expression is increased, compared to healthy individuals." (PMID 30336591, 2018). "In patients with Sjögren’s syndrome, while STX4 localizes at the basal plasma membrane, similar to healthy individuals, its expression is decreased in the apical and lateral plasma membranes." (PMID 30336591, 2018). "The intracellular expression patterns of STX3 and STX4 also dramatically change in patients with Sjögren’s syndrome." (PMID 30336591, 2018). "In labial salivary glands from the patients with Sjögren’s syndrome, syntaxin-4 and VAMP-8 expression were decreased, whereas syntaxin-3 expression was increased." (PMID 29358308, 2018). "Moreover, co-localization of STX4 and RAB3D, a small GTPase, in mature secretory vesicles in the subapical region is altered from the apical to the basolateral plasma membrane in Sjögren’s syndrome patients." (PMID 30336591, 2018).
breast carcinoma (1 paper, 2021). "Breast cancer showed the strongest correlation with the expression of STX4, the latter was associated with reduced patient survival in high expression." (PMID 34482824, 2021).
cervical squamous cell carcinoma (1 paper, 2021). A squamous cell carcinoma arising from the cervical epithelium. "According to the result of KM survival analysis, it is interesting that STX4 also played a prognostic role in cervical squamous cell carcinoma and endocervical adenocarcinoma, skin cutaneous melanoma, and uveal melanoma." (PMID 34482824, 2021).
Chlamydia infection (1 paper, 2019). "In summary, our data show that the loss of both SNAP-23 and Syntaxin 4 results in an aberrant increase in LD production during Chlamydia infection." (PMID 32025513, 2019). "Together, these results demonstrate that both, SNAP-23 and Syntaxin 4, control LD homeostasis specifically during Chlamydia infection and that this effect can be boosted with exogenous FAs." (PMID 32025513, 2019). "Rather, the role of SNAP-23 and Syntaxin 4 in the regulation of LDs is specific to Chlamydia infection." (PMID 32025513, 2019). "We then demonstrate that the loss of both of these SNARE proteins results in the dysregulation of Chlamydia-induced lipid droplets, indicating that both SNAP-23 and Syntaxin 4 play a critical role in lipid droplet homeostasis during Chlamydia infection." (PMID 32025513, 2019). "To determine whether the plasma membrane SNAREs SNAP-23, Syntaxin 3, and Syntaxin 4 play a role during Chlamydia infection, we first assessed their localization during infection." (PMID 32025513, 2019). "To identify the specific role of SNAP-23 and Syntaxin 4 during Chlamydia infection, we assessed whether Chlamydia targets the plasma membrane SNAREs to hijack secretory cargo destined for the plasma membrane." (PMID 32025513, 2019). "Thus, we investigated whether SNAP-23, Syntaxin 3 or Syntaxin 4 play a role in LD dynamics during Chlamydia infection." (PMID 32025513, 2019). "Since these SNAREs are recruited to the inclusion, we tested whether Chlamydia infection impacts Syntaxin 3/SNAP-23 and Syntaxin 4/SNAP-23 t-SNARE complex formation." (PMID 32025513, 2019). "In light of these observations, the role of SNAP-23 and Syntaxin 4 during Chlamydia infection is likely independent of constitutive secretion." (PMID 32025513, 2019). "Altogether, these data suggest that the role of SNAP-23 and Syntaxin 4 during Chlamydia infection is independent of their canonical roles in mediating membrane fusion at the plasma membrane." (PMID 32025513, 2019).
chronic myeloid leukemia (1 paper, 2021). "A research had identified the exocytosis mediator proteins STX4 in the peripheral blood neutrophils of patients with chronic myeloid leukemia early in 2004." (PMID 34482824, 2021).
cyst (1 paper, 2011). A sac-like closed membranous structure that may be empty or contain fluid or amorphous material. "Disruption of basolateral-specific targeting of syntaxin 4 (using the syntaxin 4-Δ29 deletion mutant) led to the inability of MDCK cells to form a polarized morphology in 3D cyst culture, and to a delay in tight-junction formation in 2D culture." (PMID 21698262, 2011).
embryonic carcinoma (1 paper, 2017). "For example, certain cells of the embryonic carcinoma (EC) cell line F9 extrude syntaxin-4 as membrane-tethered proteins to locally affect the morphology, motility, and cellular context of adjacent cells." (PMID 28057922, 2017). "To define the role of extruded syntaxin-4 in ES cell behavior, we used the simpler, stable embryonic carcinoma (EC) F9 stem cell system, in which ES cell–specific regulators of differentiation, including a set of Zscan4 proteins, are undetectable." (PMID 28057922, 2017). "Embryonic carcinoma cell lines F9 and P19CL6, which maintain undifferentiated states independently of Zscan4 proteins, exhibited similar cellular behaviors upon stimulation with cell surface syntaxin-4." (PMID 28057922, 2017).
Glucose intolerance (1 paper, 2021). Glucose intolerance (GI) can be defined as dysglycemia that comprises both prediabetes and diabetes. "In contrast to the glucose intolerance observed in STX1A-overexpressing mice, STX4-transgenic mice with 2–5-fold overexpression of STX4 in the skeletal muscle, adipose tissue, and pancreatic tissues, showed improved glucose homeostasis and islet function." (PMID 33673206, 2021).
Hernia (1 paper, 2021). "Therefore, these STX4 and ITGAM genes might be involved in several processes related to hernia development, such as cell adhesion and also inflammation." (PMID 34773987, 2021).
pancreatitis (1 paper, 2024). Inflammation of the pancreas. "Knockout of SNAP23 impaired the assembly of STX4‐driven basolateral exocytotic SNARE complex and STX17‐driven SNARE complex, resulting in reduction of autophagosome formation, thus protecting pancreatitis progression." (PMID 39500626, 2024).
teratocarcinoma (1 paper, 2021). A germ cell tumor characterized by the presence of an embryonal carcinoma component and a teratoma component. "Extracellular STX4 triggers the differentiation program in teratocarcinoma F9 cells that impacts cell adhesion properties." (PMID 34482824, 2021).
Type 2 diabetes (1 paper, 2025). "STX4 enrichment was sufficient to reverse Type 2 diabetes–associated mitochondrial damage in skeletal muscle by inactivation of mitochondrial fission." (PMID 41214862, 2025).
typhoid (1 paper, 2022). "Collectively, these results indicate that the last step in typhoid toxin export is controlled by the VAMP7/SNAP23/STX4 SNARE complex, which targets the typhoid toxin vesicle carrier intermediates for fusion to the plasma membrane and subsequent release of the toxin cargo to the extracellular space." (PMID 35579416, 2022).